Y_RNA (Y RNA )
Gene: Miscellaneous RNA gene on chromosome 2 (128,067,800 to 128,067,901, forward strand). Ensembl gene ENSG00000200432.
Homologues: Orthologues: chimpanzee Y_RNA (98% identical), macaque Y_RNA (94% identical), pig Y_RNA (75% identical). Paralogues in human: Y_RNA (90% identical), Y_RNA (89% identical), RNY3 (88% identical), Y_RNA (88% identical), Y_RNA (87% identical), RNY3P1 (86% identical), Y_RNA (86% identical), Y_RNA (85% identical), RNY3P14 (84% identical), RNY3P16 (84% identical), RNY3P2 (84% identical), Y_RNA (84% identical), and 96 more.